ABHD12 (abhydrolase domain containing 12, lysophospholipase)
Description:
Lysophosphatidylserine (LPS) lipase that mediates the hydrolysis of lysophosphatidylserine, a class of signaling lipids that regulates immunological and neurological processes. Represents a major lysophosphatidylserine lipase in the brain, thereby playing a key role in the central nervous system (By similarity). Prefers as substrates lysophosphatidylserines having long and very long chain acyl chains. Also able to hydrolyze oxidized phosphatidylserine; oxidized phosphatidylserine is produced in response to severe inflammatory stress and constitutes a proapoptotic 'eat me' signal. Also has monoacylglycerol (MAG) lipase activity: hydrolyzes 2-arachidonoylglycerol (2-AG), thereby acting as a regulator of endocannabinoid signaling pathways. Has a strong preference for very-long-chain lipid substrates; substrate specificity is likely due to improved catalysis and not improved substrate binding.
Synonyms: hABHD12; C20orf22; DKFZP434P106; dJ965G21.2; BEM46L2; ABHD12A; PHARC
Tractability: Small molecule: a high-quality ligand is known; it belongs to a druggable protein family. Antibody: its Gene Ontology location is reachable by antibodies, with high confidence; UniProt predicts a signal peptide or a membrane-spanning region. PROTAC: ubiquitination databases record sites on it; its protein half-life has been measured; a small molecule that binds it is known.
Target class: Enzyme; Hydrolase
Chemical probes: DO264 (high quality)
Gene: Protein-coding gene on chromosome 20 (25,294,742 to 25,390,866, reverse strand). Ensembl gene ENSG00000100997.
Subcellular location: Endoplasmic reticulum membrane
Pathways (Reactome):
Hemostasis: Arachidonate production from DAG
Gene Ontology:
Molecular function: monoacylglycerol lipase activity; phosphatidylcholine lysophospholipase activity; phosphatidylserine lysophospholipase activity; phospholipase activity; palmitoyl-(protein) hydrolase activity; phosphatidylinositol lysophospholipase activity
Biological process: acylglycerol catabolic process; glycerophospholipid catabolic process; monoacylglycerol catabolic process; phosphatidylserine catabolic process; phospholipid catabolic process; arachidonate metabolic process; macromolecule depalmitoylation; regulation of inflammatory response
Cellular component: endoplasmic reticulum membrane; membrane; plasma membrane; AMPA glutamate receptor complex; cytoplasm; dendrite cytoplasm
Genetic constraint (gnomAD): Loss-of-function variants: 37 observed, 50.33 expected, observed/expected ratio (o/e) 0.74, 90% interval 0.56 to 0.97. The upper end of that interval is the gene's LOEUF score, 0.97, which puts it in group 4 of 6, group 1 being the genes least tolerant of losing a copy. Missense variants: 510 observed, 479.88 expected, observed/expected ratio (o/e) 1.06, 90% interval 0.99 to 1.14. Synonymous variants: 211 observed, 184.35 expected, observed/expected ratio (o/e) 1.14, 90% interval 1.02 to 1.28.
Gene-disease validity (ClinGen):
ClinGen rates the evidence that ABHD12 causes each of these diseases.
PHARC syndrome (autosomal recessive): Definitive.
Homologues: Orthologues: macaque ABHD12 (99% identical), chimpanzee ABHD12 (98% identical), rat Abhd12 (93% identical), mouse Abhd12 (93% identical), guinea pig ABHD12 (93% identical), pig ABHD12 (92% identical), rabbit ABHD12 (90% identical), dog ABHD12 (85% identical), tropical clawed frog abhd12 (76% identical), zebrafish abhd12 (65% identical), Caenorhabditis elegans F01D5.7 (15% identical), Caenorhabditis elegans F01D5.8 (15% identical). Paralogues in human: ABHD12B (38% identical), ABHD17B (19% identical), ABHD17A (19% identical), ABHD13 (18% identical), ABHD17C (18% identical), ABHD16A (17% identical), ABHD16B (13% identical).
Diseases named in the same sentence as ABHD12 in open-access papers:
ABHD12 is named in the same sentence as 43 diseases in open-access papers, as found by Europe PMC text mining. Sharing a sentence is not in itself a finding about the gene and the disease. The quoted sentences say what the papers report.
Ataxia (31 papers, 2012 to 2025). Ataxia refers to impaired coordination of voluntary muscle movement. "Non-syndromic or mild phenotypes: Cases have been documented in which ABHD12 mutation carriers exhibit retinal degeneration (RP) but lack overt neuropathy, ataxia, or hearing loss even after detailed systemic evaluation." (PMID 41189896, 2025). "PHARC syndrome, a rare autosomal recessive neurodegenerative disorder caused by mutations in the ABHD12 gene, is characterized by demyelinating polyneuropathy, hearing loss, ataxia, retinitis pigmentosa (RP), and early‐onset cataracts." (PMID 39910854, 2025). "ABHD12: Pathogenic variants in ABHD12 are known to cause a complex syndrome characterized by polyneuropathy, hearing loss, ataxia, retinitis pigmentosa, and cataract (PHARC)." (PMID 40149483, 2025). "ABHD12 is associated with a combination of HL, polyneuropathy, ataxia, retinitis pigmentosa and cataracts (OMIM 612674)." (PMID 39406892, 2024). "PHARC syndrome (MIM 612674) (polyneuropathy, hearing loss, ataxia, retinitis pigmentosa, and early-onset cataract) is a neurodegenerative disorder caused by defects in the ABHD12 gene." (PMID 38891946, 2024). "Both the human counterparts of Adamts10 and Abhd12 are clinically associated with syndromic forms of cataract known as Weil-Marchesani syndrome 1 and polyneuropathy, hearing loss, ataxia, retinitis pigmentosa, and cataract syndrome, respectively." (PMID 36891866, 2023). "ABHD12 has been subsequently identified as a causal gene for the neurodegenerative disorder, polyneuropathy, hearing loss, ataxia, retinitis pigmentosa, and cataract (PHARC)." (PMID 34129148, 2021). "This study investigated the phenotypic spectrum of PHARC (polyneuropathy, hearing loss, ataxia, retinitis pigmentosa and early-onset cataract) syndrome caused by biallelic variants in the ABHD12 gene." (PMID 34573385, 2021). "PHARC (polyneuropathy, hearing loss, ataxia, retinitis pigmentosa (RP) and early-onset cataract) is an acronym for a rare, neurodegenerative disease caused by biallelic variants in the ABHD12 gene." (PMID 34573385, 2021). "Loss-of-function mutations of ABHD12 are associated with the neurodegenerative disorder polyneuropathy, hearing loss, ataxia, retinitis pigmentosa, and cataract (PHARC)." (PMID 31213981, 2019). "Similar to ABHD6, ABHD12 was originally described as a 2-AG-degrading enzyme, and mutations of ABHD12 cause the rare inherited disorder polyneuropathy, hearing loss, ataxia, retinitis pigmentosa, and early-onset cataract (PHARC)." (PMID 26491015, 2015). "Most patients with PHARC and confirmed ABHD12 mutations had ataxia, and these patients had cerebellar atrophy or peripheral polyneuropathy or both." (PMID 22938382, 2012). "Mutations of ABHD12, an enzyme hydrolyzing an endocannabinoid lipid transmitter, cause PHARC (polyneuropathy, hearing loss, ataxia, retinitis pigmentosa, and early-onset cataract)." (PMID 22938382, 2012). "Truncating ABHD12 mutations have been shown to cause PHARC, a neurodegenerative disease with polyneuropathy, hearing loss, ataxia, RP, and early cataract." (PMID 22938382, 2012). "Therefore, we recommend adding the ABHD12 gene to diagnostic gene panels for polyneuropathy, cerebellar ataxia, hearing loss, retinal dystrophy, and cataracts." (PMID 39501272, 2024). "Therefore, we recommend adding the ABHD12 gene to diagnostic gene panels for hearing loss, retinal dystrophy, cataracts, polyneuropathy and cerebellar ataxia." (PMID 39501272, 2024). "ABHD12 hydrolyzes lysophosphatidylserine (LysoPS) as a LysoPS lipase (LysoPS-specific lysophospholipase) and its genetic deletion or mutation increases LysoPS in the brain, leading to symptoms reminiscent of PHARC (polyneuropathy, hearing loss, ataxia, retinitis pigmentosa, and cataracts)." (PMID 36979406, 2023).
Ataxia (continued). "Indeed, homozygous mutation of the gene for α/β-hydrolase domain-containing 12 (ABHD12), which hydrolyzes LysoPS, causes a neurological disorder, termed polyneuropathy, hearing loss, ataxia, retinosis pigmentosa, and cataract (PHARC)." (PMID 30975169, 2019). "Although ABHD12 mutations are classically associated with PHARC syndrome, such as polyneuropathy, hearing loss, ataxia, retinopathy, and cataracts, Patient 2 exhibited binocular nystagmus but showed no additional neurological or auditory manifestations." (PMID 41189896, 2025). "Human ABHD12 mutations cause the early onset neurodegenerative disease PHARC (polyneuropathy, hearing loss, ataxia, retinitis pigmentosa, and cataracts)." (PMID 40496808, 2025). "PHARC syndrome (Polyneuropathy, Hearing loss, Ataxia, Retinitis pigmentosa (RP), and Cataracts) (MIM# 612674) is an autosomal recessive neurodegenerative disorder caused by mutations in the ABHD12 gene." (PMID 39910854, 2025). "Mutations in ABHD12 (OMIM: 613,599) are associated with polyneuropathy, hearing loss, ataxia, retinitis pigmentosa, and cataract (PHARC) syndrome (OMIM: 612674), which is a rare autosomal recessive neurodegenerative disease." (PMID 37803361, 2023). "This is the case for ABHD5 and ABHD12 causing Chanarin-Dorfmann (OMIM # 275630) and polyneuropathy, hearing loss, ataxia, retinitis pigmentosa, and cataract (PHARC; OMIM # 612674) syndromes, respectively." (PMID 34489854, 2021). "Dysfunctional ABHD12 has been linked to the rare neurodegenerative disorder called PHARC (polyneuropathy, hearing loss, ataxia, retinosis pigmentosa, cataract)." (PMID 24879289, 2014). "Mutations of another ABHD family member, ABHD12 (OMIM *613599), which results in polyneuropathy, hearing loss, ataxia, retinitis pigmentosa, and cataracts (PHARC), could also lead to cataracts." (PMID 31876103, 2020). "ABHD12 pathogenic variants lead to a rare phenotype named PHARR syndrome (MIM612674), which is a neurodegenerative disease including demyelinating Polyneuropathy, Hearing loss, cerebellar Ataxia, Retinis pigmentosa and early‐onset Cataract (PHARR)." (PMID 31393079, 2019). "Polyneuropathy, hearing loss, ataxia, retinitis pigmentosa, and cataract (PHARC) is a rare genetic human neurological disorder caused by null mutations to the Abhd12 gene, which encodes the integral membrane serine hydrolase enzyme ABHD12." (PMID 30237167, 2018). "After the identification of the ABHD12 mutation in this family, one patient underwent neurological examination which revealed ataxia, but no polyneuropathy." (PMID 22938382, 2012). "We, therefore, supplemented the EOAD- control group with ataxia genotypes that were not reported with comorbid dystonia in literature (including ABHD12; IFRD1; KIAA0226; PHYH; TDP1; VWA3B; GTF2H5; FLVCR1; ACO2; HSD17B4; DNAJC3 gene mutations; PubMed and OMIM)." (PMID 33255407, 2020). "Ataxia without cerebellar atrophy might be explained based on the cellular localization of ABHD12 in the Purkinje neurons." (PMID 34573385, 2021).
hearing loss (16 papers, 2015 to 2025). "Studies on a PHARC syndrome model, created by knocking out the ABHD12 gene in mice, revealed that as ABHD12−/− mice aged, they developed hearing impairment and abnormal motor behavior." (PMID 39910854, 2025).
cataract (13 papers, 2016 to 2025). Partial or complete opacity of the crystalline lens of one or both eyes that decreases visual acuity and eventually results in blindness. "An ABHD12 pathogenic variant was identified in a Lebanese family with USH3-like findings and cataracts." (PMID 40149483, 2025).
PHARC syndrome (12 papers, 2020 to 2025). Fiskerstrand type peripheral neuropathy is a slowly-progressive Refsum-like disorder associating signs of peripheral neuropathy with late-onset hearing loss, cataract and pigmentary retinopathy that become evident during the third decade of life. "Herein, we report a Chinese Han patient with PHARC syndrome who harbored a novel compound heterozygous variant detected in the ABHD12 gene, and whose ocular clinical phenotype was cone‐rod dystrophy." (PMID 39910854, 2025). "Our research expands the spectrum of pathogenic variants and phenotypes associated with ABHD12—PHARC syndrome." (PMID 39910854, 2025). "PHARC syndrome is caused by biallelic mutations in the ABHD12 (α/β-hydrolase domain containing 12) gene, which encodes a lyso-phosphatidylserine (lyso-PS) lipase." (PMID 39501272, 2024). "In this study, we detected a novel frameshift variant in the ABHD12 gene in two affected Iranian siblings with PHARC syndrome from a first-cousin marriage." (PMID 37803361, 2023). "We elucidated the role of a novel pathogenic mutation in the ABHD12 as a genetic reason of PHARC syndrome in an Iranian family." (PMID 37803361, 2023). "To this end, we describe the ophthalmic and associated clinical findings in patients with PHARC syndrome with biallelic ABHD12 variants." (PMID 34573385, 2021). "In this retrospective study, we report the genetic and clinical characteristics of 15 patients with PHARC syndrome with variable severity, caused by variants in the ABHD12 gene." (PMID 34573385, 2021). "In conclusion, we report the phenotype of patients with PHARC syndrome due to biallelic ABHD12 variants." (PMID 34573385, 2021). "ABHD12 KO mice and human ABHD12 nonsense mutations display progressive hearing loss within PHARC syndrome." (PMID 33329293, 2020). "We report on a patient with PHARC syndrome from a Chinese family, who harbors a compound heterozygous variant (comprising a recognized nonsense variant and a novel copy number variant) within the ABHD12 gene." (PMID 39910854, 2025). "With the continuous maturation of genetic screening technology, especially the development of NGS technology, genetic testing of such patients has revealed that the ABHD12 gene is the only one that has been identified to be associated with the pathogenesis of PHARC syndrome." (PMID 39910854, 2025). "Notably, ABHD12 was associated with another neurological disorder, PHARC syndrome, which has a clinical picture similar to that of Charcot–Marie–Tooth disease." (PMID 41444670, 2025). "In addition, identifying biallelic mutations in ABHD12 is of great importance to confirm the clinical diagnosis of PHARC syndrome." (PMID 39501272, 2024). "To date, it remains unclear where ABHD12 localizes and interacts in the inner ear, which is crucial for determining the cause of hearing loss in patients with PHARC syndrome." (PMID 34573385, 2021). "The advent of next-generation sequencing has made it possible to identify disease-causing variants on novel genes at a rapid pace and the ongoing improvements in this technology may lead to an increased detection of patients with biallelic ABHD12 variants/PHARC syndrome in the future." (PMID 34573385, 2021). "In the ER, it colocalizes with the principle brain LPS hydrolase ABHD12, responsible for the PHARC syndrome (OMIM # 612674)." (PMID 34489854, 2021). "Regarding the peripheral, more accessible tissues, a reduction in ABHD12 activity was documented in lymphoblastoid cells from a human patient with PHARC syndrome compared to healthy controls." (PMID 34489854, 2021). "However, further research is required to fully understand the cellular, molecular, and biochemical mechanisms through which ABHD12 contributes to the PHARC syndrome." (PMID 37803361, 2023). "Moreover, a summary based on mutations found so far in the ABHD12 gene did not suggest a clear genotype-phenotype correlation for PHARC syndrome." (PMID 37803361, 2023).
Usher syndrome (7 papers, 2017 to 2025). A syndromic diseae characterized by the association of sensorineural deafness (usually congenital) with retinitis pigmentosa and progressive vision loss. "Besides the USH2A gene, Usher syndrome also was caused by ABHD12 (1; 5%), CLRN1 (1; 5%), and MYO7A (8; 40%) genes." (PMID 30374144, 2018). "As for HARS, further studies are required to determine the subcellular distribution of ABHD12 in the inner ear and retina, and its interactions with other USH proteins, to confirm that there is a genuine association with Usher syndrome." (PMID 35353227, 2022). "Furthermore, genetic testing in patients with a so-called isolated form of Usher syndrome characterized by peripheral and macular retinal disease revealed biallelic mutations in ABHD12, without records of neurological investigations or neuroimaging as well." (PMID 39501272, 2024). "PDZD7 may act as a modifier gene for USH, but HARS, ABHD12, CIB2, CEP250, CEP78, ESPN, and ARSG could be grouped in a separate syndromic “deaf–blindness” category, to avoid diagnostic pitfalls and misinformation during genetic counseling for Usher syndrome." (PMID 35353227, 2022).
Cerebellar atrophy (4 papers, 2012 to 2021). Cerebellar atrophy is defined as a cerebellum with initially normal structures, in a posterior fossa with normal size, which displays enlarged fissures (interfolial spaces) in comparison to the foliae secondary to loss of tissue. "ABHD12 deficiency aggravated neuroinflammation and was closely associated with cerebellar atrophy and peripheral neuroinflammatory disease in cell models, murine PHARC and zebrafish." (PMID 29794032, 2018). "We also speculate that the heightened phagocytosis activity by microglial cells due to the loss of ABHD12, over time, also causes the cerebellar atrophy observed in human PHARC subjects." (PMID 34727579, 2021).
deafness (4 papers, 2017 to 2024). An inherited or acquired condition characterized by the complete loss of the ability to hear from one or both ears. "Notably, the proband with ABHD12 variants in FM2 had syndromic features, presenting with both characteristics of RP and deafness." (PMID 38245557, 2024).
neuropathy (4 papers, 2019 to 2025). A disorder affecting the nervous system that manifests with pain, tingling, numbness, and/or muscle weakness. "A morpholino for the ABHD12 gene was generated as part of a study on neuropathy candidate genes related to Charcot–Marie–Tooth disease." (PMID 33917666, 2021). "Hearing loss could develop simultaneously with neuropathy, in some patients with pathogenic variants in PRPS1 (n = 1), NEFL (n = 2), MPZ (n = 1), TRPV4 (n = 1); or at a distance in some cases of variants in SH3TC2 (n = 2) and ABHD12 (n = 1)." (PMID 31393079, 2019).
retinal degeneration (3 papers, 2023 to 2025). Degeneration of the retina. "While we did not observe obvious gait defects and did not test for hearing loss in Em/J mice, we note that studies of an Abhd12-related retinal phenotype are confounded since Em/J mice are also homozygous for the Pde6brd1 retinal degeneration mutation." (PMID 36891866, 2023). "Knockdown of the ABHD12 gene in mice led to neurological and auditory abnormalities, but did not result in retinal degeneration or lens opacity." (PMID 39910854, 2025).
breast carcinoma (2 papers, 2021 to 2023). "In vitro experiments revealed that USP41 and ABHD12 play an essential role in breast cancer progression, which was consistent with the results of our functional assays." (PMID 36993976, 2023). "Elucidating the detailed regulatory mechanisms of USP41 and ABHD12 may help to further understand their roles in breast cancer." (PMID 36993976, 2023). "In vitro experiments further revealed that the knockdown of ABHD12 and USP41 significantly inhibit the proliferation, invasion and migration of breast cancer cells." (PMID 36993976, 2023).